UTS2 (urotensin 2)
Description:
Highly potent vasoconstrictor.
Synonyms: U-II; UII; UCN2; PRO1068
Tractability: Small molecule: it belongs to a druggable protein family. Antibody: its Gene Ontology location is reachable by antibodies, with high confidence; UniProt places it where antibodies can reach, with medium confidence; UniProt predicts a signal peptide or a membrane-spanning region.
Gene: Protein-coding gene on chromosome 1 (7,843,083 to 7,853,512, reverse strand). Ensembl gene ENSG00000049247.
Subcellular location: Secreted
Pathways (Reactome):
Signal Transduction: G alpha (q) signalling events; Peptide ligand-binding receptors
Gene Ontology:
Molecular function: hormone activity; signaling receptor binding
Biological process: chemical synaptic transmission; muscle contraction; regulation of blood pressure; blood vessel diameter maintenance; signal transduction
Cellular component: extracellular region; synapse
Genetic constraint (gnomAD): Loss-of-function variants: 9 observed, 12.08 expected, observed/expected ratio (o/e) 0.74, 90% interval 0.45 to 1.3. The upper end of that interval is the gene's LOEUF score, 1.3, which puts it in group 5 of 6, group 1 being the genes least tolerant of losing a copy. Missense variants: 139 observed, 144.88 expected, observed/expected ratio (o/e) 0.96, 90% interval 0.83 to 1.1. Synonymous variants: 52 observed, 51.29 expected, observed/expected ratio (o/e) 1.01, 90% interval 0.81 to 1.28.
Homologues: Orthologues: macaque UTS2 (92% identical), chimpanzee UTS2 (85% identical), rabbit UTS2 (61% identical), pig UTS2 (60% identical), mouse Uts2 (48% identical), rat Uts2 (48% identical), zebrafish uts2b (30% identical), zebrafish uts2a (18% identical).
Diseases named in the same sentence as UTS2 in open-access papers:
UTS2 is named in the same sentence as 75 diseases in open-access papers, as found by Europe PMC text mining. Sharing a sentence is not in itself a finding about the gene and the disease. The quoted sentences say what the papers report.
Hypertension (17 papers, 2011 to 2025). The presence of chronic increased pressure in the systemic arterial system. "Urotensin II (UTS2) regulates vasoconstriction and is associated with a range of diseases with abnormal blood pressure regulation (e.g. hypertension, kidney disease, cirrhosis, etc.)." (PMID 36890467, 2023). "Several publications have indicated a possible relationship between UTS2 gene polymorphisms and hypertension, diabetes mellitus, Behçet’s disease, and systemic sclerosis." (PMID 27090416, 2016). "UTS2 polymorphisms have also been associated with essential hypertension." (PMID 21559414, 2011). "Indeed, the UII gene (UTS2) is associated with essential hypertension and myocardial infarction." (PMID 23293629, 2012). "Moreover, urotensin 2 inhibits insulin release, has inotropic and hypertrophic effects on heart muscle, and is a proposed biomarker of cardio-metabolic disorders including hypertension, atherosclerosis, heart failure, pulmonary hypertension, diabetes, renal failure and metabolic syndrome." (PMID 24643011, 2014). "Among these SNPs, several are relevant to disorders common in Qataris, including type 2 diabetes (UTS2), breast cancer (AKAP13), hypertension (ULK4), and nicotine dependence (FMO2)." (PMID 23139751, 2012). "A single-nucleotide polymorphism (SNP) study performed in a Hong Kong Chinese population with hypertension and diabetes indicated that UTS2 and GPR14 genes were associated with pancreatic β-cell function and insulin resistance but not hypertension." (PMID 40422232, 2025).
diabetes (14 papers, 2011 to 2025). "Several polymorphisms at the UTS2 gene have been associated with type 2 diabetes mellitus (T2DM), insulin resistance and diabetic complications such us diabetic retinopathy and carotid atherosclerosis." (PMID 21559414, 2011). "In mice with early stage diabetes, UTS2 was demonstrated to induce ER stress and EMT, which increased ECM production in tubular epithelial cells." (PMID 40422232, 2025). "Increased plasma U-II levels in patients with diabetes mellitus and elevated expression of Uts2 and its receptor in the skeletal muscle of diabetic mice were reported." (PMID 31379736, 2019). "Two diabetes related genes, coding for insulin-like growth factor (IGFBP3) and urotensin 2 (UTS2), were increasingly expressed with age which might indicate inclination of some individuals towards the development of type 2 diabetes." (PMID 22253695, 2012).
atherosclerosis (13 papers, 2012 to 2025). A disease characterized by the build-up of fatty material and calcium deposition in the arterial wall resulting in partial or complete occlusion of the arterial lumen. "In addition, GSTA4, RAPGEF3, TRPV4, INSIG1, UTS2, and PPP1R1A all play a role in the development of atherosclerosis." (PMID 39758846, 2024).
heart failure (7 papers, 2014 to 2024). Inability of the heart to pump blood at an adequate rate to meet tissue metabolic requirements. "UTS2 has already been linked to several diseases, including cardiac fibrosis, cardiac hypertrophy, and heart failure." (PMID 38639887, 2024).
metabolic syndrome (6 papers, 2011 to 2023). A cluster of metabolic risk factors for CARDIOVASCULAR DISEASES and TYPE 2 DIABETES MELLITUS. "The role of Uts2 has also been documented in kidney and liver diseases, metabolic syndrome, and type 2 diabetes." (PMID 37686217, 2023). "Finally, UTS2 gene polymorphisms are associated with myocardial infarction in individuals with and without metabolic syndrome." (PMID 21559414, 2011).
type 2 diabetes mellitus (6 papers, 2011 to 2023). A type of diabetes mellitus that is characterized by insulin resistance or desensitization and increased blood glucose levels. "A higher level of plasma Uts2 and its enhanced expression in some organs are observed in primary hypertension, atherosclerosis, arterial restenosis, heart failure, and type II diabetes mellitus." (PMID 37686217, 2023).
breast carcinoma (5 papers, 2012 to 2026). "Additionally, the likelihood of breast cancer development may be promoted by Thr21Met polymorphism in the UTS2 gene possibly through its influence on the molecular mechanisms underpinning disease pathogenesis." (PMID 34539580, 2021). "PTTG2 has been implicated in glioblastoma tumorigenesis as well as in head and neck squamous cell carcinoma, UTS2 has been reported to possess prognostic value in colorectal and breast cancers, TRAT1 in early breast cancer prognosis and DUSP1 in sarcoma progression." (PMID 39478658, 2025).
colon cancer (5 papers, 2017 to 2023). "In human, the deduced sequence of prepro-UII, cloned from colon tumor or placental library, evolved from alternative splicing of the human UTS2 gene, yielding a 124 (isoform b, NP_006777) and 139 (isoform a, NP_068835.1) amino acid variants." (PMID 28487672, 2017). "UTS2 was recently used as a new drug target towards colon cancer cells." (PMID 32375704, 2020). "We developed and validated a five-immune gene model of colon cancer, including LBP, TFR2, UCN, UTS2, and MC1R." (PMID 32375704, 2020).
renal failure (4 papers, 2014 to 2019). "It is worth noting that although protein expression for urotensin system components was high, particularly in the kidneys from the SNx‐L group that were killed immediately before renal failure, attempts to quantify Uts2, Uts2b and Uts2r (UT receptor) mRNA were unsuccessful." (PMID 30575177, 2019).
prostate carcinoma (3 papers, 2020 to 2023). A carcinoma that arises from epithelial cells of the prostate gland. "UTS2 also participates in the development of colorectal, breast, and prostate cancers." (PMID 36890467, 2023). "UTS2 (Urotensin-II) is a somatostatin-like cyclic heptapeptide and participates in the occurrence of different cancers, especially colon, breast, and prostate cancers." (PMID 33330631, 2020).
adrenal tumors (2 papers, 2012 to 2023). "Elevated levels of UTS2 mRNA have been found in human adrenal tumors compared with non-neoplastic adrenal tissues, implicating UTS2 in the progression of adrenal tumor development and steroidogenesis." (PMID 37686217, 2023).
glioma (2 papers, 2021). A benign or malignant brain and spinal cord tumor that arises from glial cells (astrocytes, oligodendrocytes, ependymal cells). "As observed in the histopathological classification, UTS2R and UTS2D were equally expressed in IDHwt or IDHmut tumors, whereas UTS2 displayed a higher expression in IDHwt gliomas, suggesting an association with malignancy." (PMID 33937253, 2021). "UTS2 was found to be significantly more expressed in astrocytoma and mostly GBM, suggesting an association with high-grade gliomas." (PMID 33937253, 2021). "Within the four groups of GBM along with the Verhaak classification, UTS2R (UT) and UTS2D (URP) were expressed in all groups of GBM, but importantly, UTS2 (UII) exhibited a net higher expression in the mesenchymal subgroup, suggesting that UII may be associated with glioma prognosis." (PMID 33937253, 2021).
adrenocortical cancer (1 paper, 2023). "Additionally, UTS2 mRNA is expressed in SW-13 cells, an adrenocortical cancer cell line, which secretes mature UTS2, indicating its potential role as a factor promoting tumor development." (PMID 37686217, 2023).
adrenocortical tumor (1 paper, 2023). "Furthermore, mRNA expression of Uts2 and its receptor is observed in certain adrenal cortex neoplasms, such as pheochromocytomas, and neuroblastomas." (PMID 37686217, 2023).
anaplastic astrocytoma (1 paper, 2021). "QPCR analyses of mRNAs encoding UII, URP, and UT in the SW1088 (anaplastic astrocytoma) and in U87, U251, 8MG, and 42MG GBM cell lines here established that expression levels were non-homogeneous and higher for UTS2R in 8MG and 42MG, UTS2 in U87, and UTS2D in SW1088." (PMID 33937253, 2021).
insomnia (1 paper, 2016). A sleep disorder characterized by difficulty in falling asleep and/or remaining asleep. "One gene in particular, Urotensin 2, was significantly down regulated, and represents a potential insomnia target, given its role in orexin regulation and rapid eye movement." (PMID 27999387, 2016).
Intrauterine Growth Restriction (1 paper, 2019). "Background and objectives: In this study, the aim was to investigate Urotensin 2 (U-II) levels and oxidant/antioxidant system parameters in pregnancies with intrauterine growth restriction (IUGR)." (PMID 31269637, 2019).
migraine (1 paper, 2016). "Although many studies have shown the roles of various genetic factors and polymorphisms in migraine disease, no studies have focused on theT21M and S89N polymorphisms in the UTS2 gene in migraine patients until now." (PMID 27090416, 2016). "The aim of this study was to analyze the plasma U-II levels along with genotype distributions and allele frequencies for UTS2 Thr21Met and Ser89Asn polymorphisms among the patients with migraine without aura (MWoA)." (PMID 27090416, 2016). "Further studies are needed for considering the role of U-II in migraine pathophysiology and for deciding if UTS2 gene may be a novel candidate gene in migraine cases." (PMID 27090416, 2016). "We detected a significant association between the T21M polymorphism in the UTS2 gene and migraine (53.8 % in patients, 40.4 % in controls, p = 0.035), but not with S89N polymorphism (p = 0.620)." (PMID 27090416, 2016). "Recently, genome-wide studies have provided new insights for genes associated with migraine disease (the ion channel gene, TRPM8, FHL5, ASTN2, and LRP1 but UTS2 gene was not one of them." (PMID 27090416, 2016).
rhabdomyosarcoma (1 paper, 2013). A rare aggressive malignant mesenchymal neoplasm arising from skeletal muscle. "Interestingly, rhabdomyosarcoma cells have often been used to study pharmacological properties of UTS2 and its receptors since these cells endogenously express UTS2 receptors." (PMID 23717650, 2013).
tumor (13 papers, 2014 to 2026). "Of the nine basal‐like‐associated cfRNA markers, five (PTTG2, RPL23AP7, UTS2, KDELC1, and DEGS1) were found to be overexpressed in basal‐like tumor tissue compared with tumors of the classical subtype within the HD tissue cohort." (PMID 39478658, 2025). "Other genes included those that encode members of the proteoglycan family (HAPLN1, SPOCK3) and influence ECM structure in the tumor microenvironment and urotensin 2 (UTS2) which has known roles in regulation of angiogenesis." (PMID 34162930, 2021). "Several biological processes in tumor biology are regulated by UTS2, including mitogenic, cell proliferation, and angiogenesis." (PMID 33330631, 2020).
vasculopathy (1 paper, 2013). "Our study also reported a dramatic induction of UTS2, a potent vasoconstrictor involved in angiogenesis and also reported preferentially expressed in skeletal muscle tissue in FSHD myoblasts, which could potentially explain the vasculopathy and skeletal muscular symptoms observed in FSHD patients." (PMID 23717650, 2013).
UTS2 also shares sentences with these, for which no sentence is quoted: renal diseases (6 papers); cardiovascular diseases (5); cardiac hypertrophy (4); chronic kidney disease (4); Insulin resistance (4); myocardial infarction (4); acute liver failure (3); Behçet’s disease (3); cancer (3); diabetic nephropathy (3); essential hypertension (3); glioblastoma (3); preeclampsia (3); renal fibrosis (3); Cirrhosis (2); congestive heart failure (2); endothelial dysfunction (2); glomerulonephritis (2); hepatocellular carcinoma (2); Obesity (2); pulmonary hypertension (2); systemic sclerosis (2); acute myocardial infarction (1); angiomyolipoma (1); aortic atherosclerosis (1); astrocytoma (1); bladder cancer (1); carotid atherosclerosis (1); Cerebral ischemia (1); colorectal cancer (1).
A further 24 diseases each share a sentence with UTS2 in 1 paper.